P2RY12 (purinergic receptor P2Y12)
Diseases named in the same sentence as P2RY12 in open-access papers (continued):
Sharing a sentence is not in itself a finding about the gene and the disease.
colorectal adenocarcinoma (1 paper, 2021). The most common type of colorectal carcinoma. "The next logical step was to determine if P2RY12 expression was specific to pancreatic adenocarcinoma, versus another digestive-tract cancer like colorectal adenocarcinoma." (PMID 34589424, 2021).
colorectal cancer (1 paper, 2024). A primary or metastatic malignant neoplasm that affects the colon or rectum. "Both are associated with better prognosis in patients with colorectal cancer and clustered with known TAM-associated genes such as P2RY12 and AIF1." (PMID 38386085, 2024).
gastric cancer (1 paper, 2025). A primary or metastatic malignant neoplasm involving the stomach. "Further in-depth analysis indicated that the genus Abiotrophia was inversely associated with eosinophils, P2RY12, and SCN4B genes, and positively linked with LGR6 in LBMI gastric cancer patients." (PMID 40041144, 2025). "g_Abiotrophia, a high-abundance dominant bacterium in LBMI with a negative correlation between LBMI and eosinophils, may inhibit P2RY12 to promote purine metabolism, modulate the TIME and thus contribute to gastric cancer development." (PMID 40041144, 2025).
influenza (1 paper, 2021). An acute viral infection of the respiratory tract, occurring in isolated cases, in epidemics, or in pandemics; it is caused by serologically different strains of viruses (influenzaviruses) designated A, B, and C, has a 3-day incubation period, and usually lasts for 3 to 10 days. "We have previously shown that RNAi silencing of P2RY12 reduces influenza replication." (PMID 34714852, 2021). "We have previously shown that RNAi silencing of P2RY12 inhibits A/WSN/33, A/CA/04/09 and B/Yamagata/16/1988 replication demonstrating its importance during replication across influenza strains and types." (PMID 34714852, 2021).
pancreatic adenocarcinoma (1 paper, 2021). "We therefore make the case that the role of P2RY12-inhibitors in cancer progression and cancer-associated-thrombosis warrants further investigation as a possible and new therapeutic target in pancreatic adenocarcinomas." (PMID 34589424, 2021).
retinal detachment (1 paper, 2023). An eye emergency condition which may lead to blindness if left untreated. "Our results showed that approximately 95.1% of CD45mid CD11b+ P2ry12+ retinal resident microglia were positive for C5aR1 expression and that 100% of resident microglia expressed C5aR1 in retinal detachment." (PMID 37443787, 2023).
type 1 von Willebrand disease (1 paper, 2015). "We previously showed that mutations in the platelet P2Y12 ADP receptor gene (P2RY12) could contribute to the bleeding phenotype in patients with type 1 von Willebrand disease." (PMID 26630678, 2015).
ZIKV infection (1 paper, 2022). "Axl and Clec7a were significantly up-regulated in response to ZIKV infection in the brain of CC071 as compared to CC001 mice while P2ry12 was significantly down-regulated." (PMID 36539803, 2022).
tumor (58 papers, 2013 to 2025). "Within the region corresponding to myeloid cells, there was separation between cells with highest expression for markers of microglia (TMEM119+ and P2RY12+) and tumor-associated macrophages (iba1+ and CD163+)." (PMID 38758780, 2024). "In conclusion, P2RY12 inhibitors diminish tumor growth and reduce metastasis formation and cancer-associated thrombosis." (PMID 34589424, 2021). "Studies have shown that P2RY12 is associated with M2-type macrophage and dendritic cell infiltration, which may affect the tumor microenvironment and cellular activities such as proliferation and migration." (PMID 40243586, 2025). "In addition, P2RY12 expression is associated with tumor grade: the expression is less in AA and GBM, as compared to A II." (PMID 28073370, 2017). "TAM_C showed the highest expression of P2ry12, which along with their localization outside of the tumor mass, suggests they are predominantly brain-resident microglia." (PMID 38622132, 2024). "Expression of P2RY12 by microglia and platelets in gliomas is thought to promote the proliferative capacity and chemotaxis of tumor cells." (PMID 38275375, 2023). "Expression of the purinergic receptor P2RY12 has been described in several tumor types, but its significance is poorly understood." (PMID 38275375, 2023). "We found HLA-DR, Iba1, CD68, TREM2, P2RY12, CD64, CD16 and CD32a immunolabelled tumour-associated microglia and perivascular macrophages in the tumour cores." (PMID 37324244, 2023). "Taken together, our results show that clopidogrel or other P2RY12 inhibitors can significantly decrease the tumor growth and metastatic spread by inhibiting cell migration and proliferation." (PMID 34589424, 2021). "Our results support that the P2RY12 blockade inhibits different molecular mechanisms that result in a diminished tumor growth and impaired metastatic spread." (PMID 34589424, 2021). "The Hom-MG-1 subgroup highly expressed the innate characteristic genes of microglia (Tmem119, P2ry12, Crybb1, Cst1, Gpr34, and Cx3cr1), poorly expressed tumor activation-related genes, and expressed early activation genes to a certain extent (Jun, Junb, Jund, and Fos)." (PMID 39867913, 2024). "Tumor-associated macrophages (TAMs) further divided into monocyte-derived brain macrophages (Mo-TAMs) expressed monocyte markers (TGFBI, VCAN, LYZ, and CLEC12A) and cells termed as Mg-TAMs expressed microglial signature genes (TMEM119, P2RY12, and P2RY13)." (PMID 39451239, 2024). "Histological evaluation of qMCP-deficient and WT tumors showed reduction of tumor-associated macrophages by IBA1 staining with no changes in P2RY12, CD31, OLIG2, GFAP, and CD44 positive areas." (PMID 37012245, 2023). "For this analysis, the tumor samples were stratified into high and low microglia content, using a score range from 0 to 3 depending on the presence of different amounts of these cells determined by immunohistochemical (IHC) staining with the microglial marker P2RY12." (PMID 39744679, 2025). "Protein-protein interaction (PPI) and Cox regression analysis were performed on the differentially expressed genes (DEGs) to identify four key tumor microenvironment (TME) -related genes (CCR2, CCR4, P2RY12, and P2RY13)." (PMID 33318300, 2020). "Moreover, the overexpression of GFP and P2RY12 might play a role in regulating gene expression and alternative splicing concerning apoptosis and cell proliferation, which serves as an experimental foundation for gaining further insights into the mechanisms of action within tumor cells." (PMID 40243586, 2025). "Similarly, expression of the microglia homeostatic genes P2RY12 and CX3CR1 declined with tumor grade, while expression of the immunosuppressive genes IL10 and F11R (JAM-A) increased with tumor grade." (PMID 38895459, 2025).
tumor (continued). "More specifically, in densely cellular tumor regions, P2RY12+ microglia were absent when tumors harbor high abundance of CD163+ macrophages." (PMID 39352749, 2024). "Microglial markers SALL1, TMEM119, and P2RY12 were minimally expressed among tumor-infiltrating cells, suggesting that microglia did not highly infiltrate the brain metastases in this patient." (PMID 37209684, 2023). "In the tumor periphery, PTPRC+CD68+ immune cells expressed P2RY12, a marker of microglia." (PMID 36266311, 2022). "To date, the differential expression of P2RY12 in different tumor-types and its role in cancer development has not been explored." (PMID 34589424, 2021). "Both P2RY12 and TMEM119 expression were retained in tumor tissue." (PMID 34286275, 2021). "To further clarify the mechanism underlying the functions of the four previously discovered key genes (CCR2, CCR4, P2RY12, and P2RY13) in the tumor microenvironment, we divided LUAD patients into high-expression groups and low-expression groups according to the four gene expression levels." (PMID 33318300, 2020).
cancer (46 papers, 2015 to 2026). A tumor composed of atypical neoplastic, often pleomorphic cells that invade other tissues. "We previously demonstrated that drugs targeting the platelet receptor P2RY12 reduced cancer progression and cancer-associated thrombosis in mice." (PMID 34589424, 2021). "Since cancer is associated to a pro-inflammatory state, it is logical that P2RY12 inhibition could positively impact the tumoral microenvironment by reducing the pro-inflammatory signals." (PMID 34589424, 2021). "Selective P2RY12 antagonists attenuate microglia activation, mechanical allodynia, and thermal hyperalgesia in models of neuropathic, inflammatory, and cancer pain." (PMID 34954381, 2022). "Still, more clinical studies are needed to fully understand the role of P2RY12 in different cancer types before including this molecule in future clinical trials." (PMID 34589424, 2021). "We can conclude that P2RY12 plays an important role in the migration and proliferation of cancer cells." (PMID 34589424, 2021). "Another type of platelet-inhibitors, those that target the ADP-binding receptor P2RY12, have recently began taking the spotlight in cancer research." (PMID 34589424, 2021). "P2RY12 blockade also inhibits cancer-cell P2RY12 activation, resulting in a direct decrease in cancer-cell proliferation and migration." (PMID 34589424, 2021). "Additionally, they established that P2RY12 activation on cancer cells induces cell proliferation through EGFR signaling." (PMID 34589424, 2021). "Indeed, P2RY12 inhibitors not only stopped the formation of spontaneous aggregates in our advanced-stage-cancer model, but it did so with a smaller impact on the tail bleeding time than aspirin." (PMID 34589424, 2021). "Further studies will be required to determine which type of cancers express P2RY12 and could then be potentially treated with anti-P2RY12 drugs." (PMID 34589424, 2021). "In addition, we found that the heightened expression of GFP and P2RY12 might affect the regulation of genes related to the growth of cancer cells." (PMID 40243586, 2025). "We have also shown how P2RY12 expression could be specific to PDACs, opening new gates for researchers to determine its utility as a biomarker of malignant pancreatic disease or targeted cancer therapy." (PMID 34589424, 2021).
cardiovascular diseases (28 papers, 2008 to 2025). "In cardiovascular disease, ADP is a key regulator of platelet activity and inhibition of the purinergic receptor P2Y12 has thus emerged as an important therapeutic strategy to reduce recurrent cardiovascular events." (PMID 35353230, 2022).
neurodegenerative disease (13 papers, 2020 to 2025). A disorder of the central nervous system characterized by gradual and progressive loss of neural tissue and neurologic function. "Microglia in the uninflamed brain exhibit a homeostatic genetic signature, expressing mRNAs for P2ry12, Cx3cr1, Temem119, Siglech, Hexb, and Fcrls, which are all downregulated during aging and in neurodegenerative diseases associated with cognitive disruption." (PMID 36153630, 2022). "While microglial core genes (e.g., TMEM119 and P2RY12) were found to be conserved, differences between human and mouse microglial gene expression were apparent in genes responsible for phagocytosis, complement, and susceptibility to neurodegenerative diseases." (PMID 33540859, 2021). "The expression of microglial signature genes, including TMEM119, P2RY12, and CX3CR1, is gradually reduced with age or in neurodegenerative diseases, suggesting the loss of homeostatic microglial function." (PMID 34920745, 2021). "In mouse models of neurodegenerative diseases including AD, P2RY12 immunoreactivity in the brain is reduced at onset and disease peak but restored during recovery." (PMID 33269098, 2020). "No direct links between P2RY12 and PD have been reported in the literature, but P2RY12 is a widely studied gene with roles suggested in neuroinflammation, apoptosis, and autophagy, pathways that are relevant to PD and other neurodegenerative diseases." (PMID 32864809, 2020).
infection (12 papers, 2015 to 2026). The state of being infected such as from the introduction of a foreign agent such as serum, vaccine, antigenic substance or organism. "In response to either Aβ pathology or MA10 infection, microglia shared only four significantly down-regulated DEGs (Csf1r, P2ry12, Cx3cr1, Hexb), all of which are signature microglial homeostatic markers." (PMID 41497643, 2025). "This was due to a combination of P2RY12 downregulation only on P2RY12lo cells and an increase in the proportion of this subset over the course of infection." (PMID 34311763, 2021).
inflammation (4 papers, 2013 to 2022). Aberrant reaction of the microcirculation characterized by movement of fluid and leukocytes from the blood into extravascular tissues. "The P2RY12 (P2Y12 receptor) mediates LTE4-induced pulmonary inflammation in studies when using Chinese hamster ovary cells transfected with human P2Y12 constructs." (PMID 36292755, 2022).
neurological diseases (4 papers, 2019 to 2025). "For instance, key microglial homeostatic signature genes such as P2RY12 and spalt-like transcription factor 1 (SALL1) are implicated in neurological diseases, and their study will benefit from systems in which they are highly expressed at baseline." (PMID 40231345, 2025).
brain diseases (1 paper, 2021). "Moreover, immune and hemorheological effects should also be considered as a potential mechanism of action of the systemic administration of P2RY12 antagonists in the outcome of brain diseases." (PMID 33561958, 2021). "However, targeting P2RY12 with antagonists in brain diseases only makes sense under the assumption that ATP (required to activate P2RY12) is a danger signal in brain diseases." (PMID 33561958, 2021).
psychiatric disorder (1 paper, 2025). A disorder characterized by behavioral and/or psychological abnormalities, often accompanied by physical symptoms. "Interestingly, we found that 10Hz flicker mitigated stress-induced changes in transcription of microglial receptors P2ry12 and stress associated receptors such as Nr3c1 and Tlr4, as well as microglial Igfbp2, a key gene implicated in affective and psychiatric disorders." (PMID 40791511, 2025).
P2RY12 also shares sentences with these, for which no sentence is quoted: myocardial infarction (115 papers); coronary artery disease (61); atrial fibrillation (42); Hypertension (33); acute myocardial infarction (19); ST Elevation Myocardial Infarction (19); chronic kidney disease (18); cardiac arrest (13); Thrombosis (13); angina (11); heart failure (9); endothelial dysfunction (8); Arterial thrombosis (7); peripheral artery disease (7); migraine (6); ovarian carcinoma (6); Thrombocytopenia (6); transient ischemic attack (6); type 2 diabetes (6); anemia (5); hyperlipidemia (5); unstable angina (5); alcohol abuse (4); dyslipidemia (4); heart disease (4); hemorrhagic stroke (4); intracranial hemorrhage (4); Parkinson disease (4); pulmonary embolism (4); cardiogenic shock (3).
A further 116 diseases each share a sentence with P2RY12 in 3 papers or fewer.